ENSG00000278334
Gene: Miscellaneous RNA gene on chromosome 7 (27,185,832 to 27,186,018, forward strand). Ensembl gene ENSG00000278334.
Gene Ontology:
Biological process: negative regulation of gene expression
Homologues: Orthologues: mouse Gm56037 (91% identical).